ZIC2 (Zic family zinc finger 2)
Description:
Acts as a transcriptional activator or repressor. Plays important roles in the early stage of organogenesis of the CNS. Activates the transcription of the serotonin transporter SERT in uncrossed ipsilateral retinal ganglion cells (iRGCs) to refine eye-specific projections in primary visual targets. Its transcriptional activity is repressed by MDFIC. Involved in the formation of the ipsilateral retinal projection at the optic chiasm midline. Drives the expression of EPHB1 on ipsilaterally projecting growth cones. Binds to the minimal GLI-consensus sequence 5'-TGGGTGGTC-3'. Associates to the basal SERT promoter region from ventrotemporal retinal segments of retinal embryos.
Synonyms: HPE5
Tractability: PROTAC: UniProt records ubiquitination sites on it; ubiquitination databases record sites on it.
Gene: Protein-coding gene on chromosome 13 (99,981,784 to 99,986,765, forward strand). Ensembl gene ENSG00000043355.
Subcellular location: Nucleus; Cytoplasm
Subcellular location (Human Protein Atlas): Nuclear bodies
Pathways (Reactome):
Developmental Biology: Formation of the anterior neural plate
Gene Ontology:
Molecular function: protein binding; chromatin DNA binding; DNA binding; DNA-binding transcription factor activity; DNA-binding transcription factor activity, RNA polymerase II-specific; RNA polymerase II cis-regulatory region sequence-specific DNA binding; RNA polymerase II transcription regulatory region sequence-specific DNA binding
Biological process: brain development; central nervous system development; negative regulation of DNA-templated transcription; positive regulation of DNA-templated transcription; regulation of transcription by RNA polymerase II; visual perception
Cellular component: nuclear body; cytoplasm; nucleus
Genetic constraint (gnomAD): Loss-of-function variants: 6 observed, 22.78 expected, observed/expected ratio (o/e) 0.26, 90% interval 0.14 to 0.52. The synonymous counts are far from expectation, so gnomAD's model fits this gene poorly and the ratio says little. Missense variants: 566 observed, 597.45 expected, observed/expected ratio (o/e) 0.95, 90% interval 0.88 to 1.02. Synonymous variants: 386 observed, 276.33 expected, observed/expected ratio (o/e) 1.4, 90% interval 1.28 to 1.52.
Homologues: Orthologues: chimpanzee ZIC2 (100% identical), macaque ZIC2 (99% identical), pig ZIC2 (98% identical), mouse Zic2 (98% identical), dog ZIC2 (98% identical), guinea pig ZIC2 (97% identical), rat Zic2 (92% identical), tropical clawed frog zic2 (75% identical), zebrafish zic2a (74% identical), zebrafish zic2b (61% identical). Paralogues in human: ZIC1 (65% identical), ZIC3 (60% identical), ZIC5 (45% identical), ZIC4 (38% identical), GLI2 (33% identical), GLI3 (30% identical), GLIS3 (26% identical), GLI1 (25% identical), GLIS1 (22% identical), GLIS2 (21% identical), ZXDA (20% identical), ZXDB (20% identical), and 2 more.
Diseases named in the same sentence as ZIC2 in open-access papers:
ZIC2 is named in the same sentence as 88 diseases in open-access papers, as found by Europe PMC text mining. Sharing a sentence is not in itself a finding about the gene and the disease. The quoted sentences say what the papers report.
holoprosencephaly (30 papers, 2006 to 2025). Holoprosencephaly (HPE) is a complex brain malformation resulting from incomplete cleavage of the prosencephalon, occurring between the 18th and 28th day of gestation, and affecting both the forebrain and face, which results in neurological manifestations and facial anomalies of variable severity. "Individuals with holoprosencephaly harboring ZIC2 variants present with bitemporal narrowing, upslanting palpebral fissures, a short nose with anteverted nares, a broad and well demarcated philtrum, and large ears." (PMID 39226899, 2024). "In terms of human genetic disease, Zic2 loss-of-function mutations are well known to cause the severe brain defect holoprosencephaly." (PMID 36916392, 2023). "In humans, ZIC2 mutations are the second-most-common known cause (after SHH mutations) of the severe brain defect holoprosencephaly, in which the cerebral hemispheres fail to separate fully, owing to faulty midline specification." (PMID 36916392, 2023). "ZIC2 encodes a human homolog of the Drosophila Odd-paired (Opa) transcription factor and is disrupted in ∼5% of holoprosencephaly patients." (PMID 37855680, 2023). "Both TGIF and ZIC2 are mutated in holoprosencephaly, a disorder caused by a failure in embryonic forebrain development, whereas MYCN mutations cause Feingold and megalocephaly syndromes, which are associated with reduced and increased brain size, respectively." (PMID 35438231, 2022). "It is known that the same mutation can lead to different phenotypes in the holoprosencephaly spectrum within the same family with markedly different severity, even in monozygotic twins with the same ZIC2 mutation." (PMID 34576017, 2021). "ZIC2 in 13q23.3 (cases 23–25) has been identified as a key gene associated with several major CFMs resulting from holoprosencephaly." (PMID 32863884, 2020). "Mutations in ZIC2 gene, involving expansion of an alanine repeat at C-terminus, cause holoprosencephaly-5, a structural anomaly of the human brain." (PMID 30423812, 2018). "ZIC2 mutation is one of four principal genetic risk factors for holoprosencephaly (HPE), the most common structural brain disease." (PMID 29992973, 2018). "ZIC2 is the only ZIC genes known to be associated with both major forms of holoprosencephaly (HPE): classic HPE and midline interhemispheric HPE 37, and it has been recently demonstrated to inhibit Wnt/β‐catenin protein signalling." (PMID 28707430, 2017). "Mutations on six3 or zic2 lead to holoprosencephaly and cyclopia (partially fused optic vesicles) in humans, also suggesting a role of these genes in the morphogenetic reorganization underlying optic vesicle evagination." (PMID 23892006, 2013). "Consistently in humans, clinical data has revealed that mutations in human ZIC2 account for a large number of cases of the neural tube closure defect, holoprosencephaly, one of the most common congenital abnormalities in humans." (PMID 23555929, 2013). "Experimental murine alleles of Zic2 are implicated in neurulation delay, neural tube defects and a spectrum of holoprosencephaly phenotypes." (PMID 22859937, 2012). "All putative target genes have been reported to play important roles in developmental processes: Zic2 and 5 are zinc finger proteins of the cerebellum, and mutations in the zic2 gene have been reported to cause holoprosencephaly." (PMID 22069375, 2011). "This indicated that the ZIC2 gene was the principal cause of holoprosencephaly in the patient." (PMID 38280885, 2024). "Although CMA was performed on all simplex cases (n = 141), a causal variant was identified in the form of chromosomal deletion in only three cases (14DG1134, 16DG1465, and 15DG0267); the latter is a case of holoprosencephaly linked to a large homozygous deletion that encompasses ZIC2 and ZIC5." (PMID 34645488, 2021). "One of the causal genes for holoprosencephaly (HPE) is ZIC2 (HPE5)." (PMID 29391420, 2018).
holoprosencephaly (continued). "Additionally, mutations in human zic2 lead to holoprosencephaly, a midline defect of the anterior due to perturbed organizer function." (PMID 24992682, 2014). "Mutations in this region have been associated with holoprosencephaly in humans and are thus hypothesized to disrupt Zic2 function." (PMID 23555929, 2013). "Further, mutations in human ZIC2 result in holoprosencephaly (HPE), a forebrain defect where the cerebral hemispheres fail to separate during development and HPE phenotypes have been connected to aberrant RA signaling, thus providing a plausible link between Zic2 and retinoic acid metabolism." (PMID 23937294, 2013). "Mutations in zic2 in mice and humans also cause holoprosencephaly." (PMID 17996054, 2007). "Extra-craniofacial defects, including cardiovascular, visceral and urino-genital anomalies have previously been noted in patients with holoprosencephaly (HPE) carrying ZIC2 mutations, but the details of these malformations have not previously been documented." (PMID 29992973, 2018). "Coding region alterations of ZIC2 are the second most common type of mutation in holoprosencephaly (HPE)." (PMID 22859937, 2012). "Our data nevertheless explain the co-morbidity of holoprosencephaly with congenital heart disease and suggest that ZIC2 should be considered as a candidate for screening for the latter disease." (PMID 29992973, 2018). "Zic2 knockdown mice show a strong holoprosencephaly phenotype in which the cerebral hemispheres are fused, and structures derived from the dorsal midline of forebrain are missing or reduced." (PMID 17274816, 2007). "Other gene mutations that relates to holoprosencephaly, including ZIC2, SIX3, TGIF1, CDON, FGFR1, CENPF and DHCR7, were not identified." (PMID 39859210, 2025). "Aberrant ZIC-gene expression during embryogenesis may entail Dandy-Walker malformation (Zic1 and Zic4), neural tube defects (Zic2), holoprosencephaly (Zic2), and heterotaxy syndrome (Zic5)." (PMID 32450842, 2020). "In this report, we explore the likelihood that presumed regulatory regions in the vicinity of the ZIC2 gene might be the target of genetic variation that could directly or indirectly influence the presence or manifestations of holoprosencephaly phenotypes." (PMID 22859937, 2012). "Zic2 is one of the few genes, independent of the hedgehog pathway, linked to the severe and prevalent congenital malformation of the forebrain termed holoprosencephaly in humans (HPE)." (PMID 21826240, 2011). "Third, while some progress has been made in understanding holoprosencephaly (HPE)—particularly through the identification of variants in genes such as SHH, SIX3, ZIC2, and TGIF1—most of these findings originate from non-Latin American cohorts." (PMID 40700109, 2025). "They found that the usual mutations associated with human holoprosencephaly (SHH, TGIF, ZIC2 and SIX3) and GLI 3 were not present, and cholesterol studies were normal." (PMID 34576017, 2021). "Rare cases (about 5%) of severe SLO partients exhibit holoprosencephaly-like features without mutations in the main holoprosencephaly genes SHH, ZIC2, SIX3 and TGIF." (PMID 34576017, 2021).
breast carcinoma (12 papers, 2020 to 2025). "Moreover, in vitro experiments were completed to further explore the biological functions of ZIC2 gene (one of the risk genes in the prognostic model) in breast cancer." (PMID 37596527, 2023). "There is mounting evidence of the oncogenic influence of ZIC2 expression in human cancers, and high expression of ZIC2 has been found in nasopharyngeal cancer, breast cancer, and prostate cancer." (PMID 38304730, 2024). "ZIC2 expression at the transcriptome level in breast cancer cell lines was displayed using the database of CCLE and RT-qPCR." (PMID 37596527, 2023). "We focused on the expression, clinical significance and prognostic value of ZIC2 in breast cancer to further confirm the prognostic signature." (PMID 37596527, 2023). "miR-1284, miR-129-5p and miR-1271‐5p can also downregulate ZIC2 expression in breast cancer, prostate cancer, cervical cancer, acute myeloid leukemia and liver cancer, respectively 25-29." (PMID 37496990, 2023). "Then, the results of CCK-8 assay, cellular migration assay and cell cycle assay showed that the down-regulation of ZIC2 gene expression inhibited the cell viability, cellular migration, and cell cycle of breast cancer cells." (PMID 37596527, 2023). "In breast cancer, low expression of ZIC2 has been correlated with poor outcomes and acts as a tumor suppressor by regulating STAT3." (PMID 35565241, 2022). "The reason for its positive relationship with prognosis in breast cancer is because in this cancer, Zic2 directly represses STAT3 transcription." (PMID 34099631, 2021). "Numerous studies have found that the ZIC2 gene is expressed abnormally in a various solid tumors including breast cancer, nasopharyngeal cancer, and cervical cancer." (PMID 33439969, 2021). "ZIC2 was also highly expressed in breast cancer tissues, promoting the proliferation, migration and invasion of breast cancer cells." (PMID 33665207, 2021). "ZIC2 can be utilized as a useful prognostic indicator in breast cancer and exerts a tumor suppressor effect by regulating STAT3." (PMID 34122521, 2021). "ZIC2 can promote the malignant progression of various cancers, such as liver cancer, nasopharyngeal cancer, breast cancer, cervical cancer and so on." (PMID 32819300, 2020). "In addition, further experimental studies should be conducted to unravel the mechanism by which ZIC2 mediates the malignant function of breast cancer cells, resulting in a poor prognosis for patients." (PMID 37596527, 2023). "There is currently limited evidence on the role of ZIC2 in breast cancer." (PMID 37596527, 2023). "The mRNA and protein expression levels of breast cancer cell lines were determined, showing that ZIC2 may act as an independent prognostic factor in breast cancer." (PMID 37596527, 2023). "Furthermore, down-regulation of ZIC2 gene expression inhibited the cell viability, cellular migration and cell cycle of breast cancer cells." (PMID 37596527, 2023). "However, Zic2 is barely expressed in breast cancer, in which high Zic2 expression predicts better survival." (PMID 34099631, 2021). "Knockdown of Zic2 inhibited the proliferation, migration, and invasion of breast cancer cells." (PMID 33767130, 2021). "Additionally, ZIC2 is used to inhibit breast cancer cell proliferation, migration, and invasion as it is a target gene of miR-1284." (PMID 34122521, 2021). "The in vitro experiments revealed that the down-regulation of ZIC2 gene expression inhibited the cell viability, cellular migration, and cell cycle of breast cancer cells, and ZIC2 might serve as a therapeutic target for breast cancer." (PMID 37596527, 2023). "For example, ZIC2 is highly expressed in HCC, bone cancer, and cervical cancer, whereas it is less expressed in breast cancer, thyroid cancer, and gastric cancer." (PMID 33439969, 2021). "In our study, the expression level of ZIC2 in the TCGA databases were negative correlated with OS of breast cancer patients." (PMID 37596527, 2023).
breast carcinoma (continued). "ZIC2 can transcriptional regulates Src, lncRNA SNHG12, Axin2, Runx2, OCT4, STAT3, PAK4 expression in non-small cell lung cancer, endometrial cancer, colon cancer, ccRCC, lung adenocarcinoma, liver cancer, and breast cancer 15, 28, 36-41." (PMID 37496990, 2023).
liver cancer (12 papers, 2017 to 2025). An epithelial or non-epithelial malignant neoplasm that arises from the liver. "The findings of this report support the involvement of ZIC2 in immune interaction mechanisms underlying liver cancer tumors." (PMID 33439969, 2021). "In particular, this study revealed that ZIC2 expression is associated with the levels of immune cell infiltration in liver cancer." (PMID 33439969, 2021). "In the present study, we found that ZIC2 was associated with differential gene expression in liver cancer tissues and normal tissues using the GEPIA database." (PMID 33439969, 2021). "Moreover, differentially expression of ZIC2 was associated with the survival prognosis of patients with liver cancer as determined using the Kaplan-Meier Plotter database tool." (PMID 33439969, 2021). "GO enrichment analysis indicated that high ZIC2 expression in patients with liver cancer might be associated mainly with the cell cycle." (PMID 33439969, 2021). "Previous studies suggest that ZIC2 can serve as a prognostic biomarker, correlating with poor prognosis and high immune infiltration of liver cancer." (PMID 40520016, 2025). "On the contrary, Zic2 is highly expressed in liver cancer and embryonic stem cells and drives the self-renewal of liver CSCs through directly targeting Oct4." (PMID 38933287, 2023). "The analysis results of the GEPIA database revealed that compared with normal tissues, the level of mRNA expression of ZIC2 gene in liver cancer tissues was significantly higher (P<0.05)." (PMID 33439969, 2021). "Therefore, we predict that ZIC2 may be a crucial gene involved in the frontline response of immune cells, and may be associated with immune infiltration and prognostic biomarkers in patients with liver cancer." (PMID 33439969, 2021). "CD4+ T cell patients with high expression of ZIC2 mRNA in liver cancer had a better 5-year survival prognosis, as analyzed through the Timer database." (PMID 33439969, 2021). "The OS and PFS of patients with high ZIC2 expression in liver cancer were significantly lower than those of patients with lower ZIC2 expression." (PMID 33439969, 2021). "ZIC2, a zinc finger transcription factor, was required for the self-renewal maintenance of liver cancer stem cells, and its depletion reduced sphere formation and xenograft tumor growth in mice." (PMID 32370292, 2020). "Molecular studies delineated the mechanism of ZIC2 activity on liver cancer stem cells: ZIC2 recruits the nuclear remodeling transcription factor (NURF) complex to the OCT4 promoter, promoting OCT4 activation." (PMID 28930164, 2017). "Moreover, ZIC2 regulates the expression of PAK4 by binding to the promoter of PAK4 to promote liver cancer progression." (PMID 37479694, 2023). "Therefore, it is of great clinical significance to study the expression of ZIC2 gene in liver cancer, the clinical prognosis of patients with liver cancer, and the potential relationship and mechanisms involving ZIC2 gene and tumor immune system interactions." (PMID 33439969, 2021). "Moreover, ZIC2 plays an important role in the progression, invasion, and metastasis of liver cancer." (PMID 33439969, 2021). "In particular, the present study revealed that ZIC2 gene expression was positively correlated with immune infiltrating cells in patients with liver cancer, and suggests that ZIC2 can be used as a prognostic biomarker to evaluate low prognosis and high immune infiltration of liver cancer." (PMID 33439969, 2021). "Moreover, we used the TIMER database to study the correlation between ZIC2 and tumor infiltrating immune cells in the liver cancer microenvironment." (PMID 33439969, 2021). "With further research, ZIC2 may represent the gene target for predicting the response of liver cancer immunotherapy in the future." (PMID 33439969, 2021). "Interestingly, ZIC2-dependent OCT4 expression was involved in regulating CSC traits in liver cancer." (PMID 32922547, 2020).
liver cancer (continued). "Moreover, ZIC2 is highly and specifically expressed in liver cancer stem cells (CSCs) and is essential for the self-renewal maintenance of liver CSCs." (PMID 28835494, 2017). "ZIC2 knockdown induced a reduction of liver sphere formation and of tumor xenograft in mice, thus supporting the idea that transcription factor is required for liver cancer stem cell self-renewal." (PMID 28930164, 2017). "Some studies revealed that ZIC2 could regulate the progression of several types of cancer, including nasopharyngeal carcinoma, bladder cancer, and liver cancer." (PMID 33209196, 2020). "Interestingly, the association between ZIC2 and OCT4 is reported in liver cancer." (PMID 32922547, 2020). "It has been shown that ZIC2 acts as an important activator, recruiting the nuclear remodeling factor (NURF) complex to initiate Oct4 expression and maintain self-renewal in liver cancer stem cells." (PMID 28835494, 2017). "ZIC2 can activate TGF-β, Src/FAK, Notch, Raf/MEK/ERK, and Wnt/β-catenin signaling pathway in colorectal cancer, non-small cell lung cancer, endometrial cancer, liver cancer, and ccRCC cells 28, 35-39." (PMID 37496990, 2023). "Surprisingly, the expression of ZIC2 mRNA revealed a significant positive correlation with tumor purity, and with B cell, CD8+ T cell, CD4+ T cell, macrophage, neutrophil, and dendritic cell infiltration in the immune microenvironment of liver cancer (Timer database, Cor > 0, P<0.001)." (PMID 33439969, 2021).